DDX21 (DExD-box helicase 21)
Diseases named in the same sentence as DDX21 in open-access papers (continued):
Sharing a sentence is not in itself a finding about the gene and the disease.
colorectal cancer (20 papers, 2018 to 2026). A primary or metastatic malignant neoplasm that affects the colon or rectum. "The results of this study indicate that RRP9 and DDX21 are overexpressed in both colorectal cancer and keloids, and their high expression is associated with worsened prognosis." (PMID 37988222, 2023). "The literature reviewed above is consistent with the findings of our study, where increased expression of DDX21 is associated with a poorer prognosis in both colorectal cancer and keloids." (PMID 37988222, 2023). "Survival analysis showed that high DDX21 expression was associated with the survival of the patients with early colorectal cancer." (PMID 37988222, 2023). "To explore possible roles of autoimmune recognition in cancer immunity, we examined DDX21 protein expression in colorectal cancer tissue and its association with patient clinical outcomes." (PMID 33328538, 2020). "In conclusion, our findings establish DDX21 as a crucial regulator of dormancy-like phenotype in colorectal cancer cells and highlight its potential as a biomarker for dormancy-like tumor populations, radioresistance and poor clinical outcomes in CRC." (PMID 42071007, 2026). "Gene effect scores for DDX21 and BIRC5, derived from CRISPR-Cas9 loss-of-function screens across 40 colorectal cancer (CRC) cell lines in the Achilles project, were −0.8 and −1.5, respectively." (PMID 40362385, 2025). "DExD- box helicase 21 (DDX21) is overexpressed in colorectal cancer (CRC) and is positively correlated with poor prognosis and the malignant phenotype of CRC." (PMID 40301349, 2025). "Studies have shown that DDX21 is overexpressed in colorectal cancer and plays a significant role in its development." (PMID 39769343, 2024). "Beyond breast and colorectal cancers, the significance of DDX21 extends across a broad spectrum of neoplastic disorders." (PMID 39769343, 2024). "RRP9 and DDX21 exhibit high expression and significant roles in patients suffering from colorectal cancer and keloids." (PMID 37988222, 2023). "We found that the core genes (RRP9 and DDX21) were highly expressed in colorectal cancer and scar tissue samples, while their expression was lower in normal samples." (PMID 37988222, 2023). "Heatmaps were generated to visualize the expression levels of core genes (RRP9 and DDX21) in the batch-corrected matrix of colorectal cancer and scar tissue datasets." (PMID 37988222, 2023). "The Western blot (WB) results indicate that the core genes RRP9 and DDX21 are highly expressed in both early and late-stage colorectal cancer, with a more significant expression level observed in the late-stage." (PMID 37988222, 2023). "The polymerase chain reaction (PCR) results reveal that the core genes RRP9 and DDX21 are highly expressed in both colorectal cancer and scar tissue." (PMID 37988222, 2023). "The higher expression of DDX21 in colorectal cancer and keloids, the higher the DDX21, the worse the prognosis." (PMID 37988222, 2023). "Unbiased deep proteomic profiling of two independent colorectal cancer cohorts using mass spectrometry showed that DDX21 protein was significantly upregulated in cancer relative to benign mucosa." (PMID 33328538, 2020). "We then examined DDX21 protein expression in a validation group of 710 patients, 619 of whom with early stage and 91 with late stage colorectal cancers." (PMID 33328538, 2020). "In summary, we identified DDX21 autoantigen as a potential prognostic marker for the MSI subtype of early stage colorectal cancer." (PMID 33328538, 2020). "We validated DDX21 protein expression in a large cohort of patients in order to evaluate the clinical prognostic significance of DDX21 in colorectal cancer, especially its potential as a prognostic marker for early stage cancer." (PMID 33328538, 2020). "To explore associations between DDX21 protein expression and clinicopathological features of colorectal cancer, we evaluated the expression level of DDX21 in each tissue in a semi-quantitative fashion." (PMID 33328538, 2020).
colorectal cancer (continued). "We investigated DDX21 protein expression in 710 colorectal cancer cases using tissue microarrays, which included a large cohort of 619 patients with early stage (stages I and II) cancer and a cohort of 91 patients with late stage (stages III and IV) cancer." (PMID 33328538, 2020). "In the early stage colorectal cancer cohort, positive DDX21 expression was detected in 28.1% (63/224) of stage I and 20.5% (81/395) of stage II patients." (PMID 33328538, 2020). "To evaluate the prognostic potential of DDX21 protein expression for colorectal cancer, we investigated the relationship between patient survival times and DDX21 using Kaplan–Meier analyses." (PMID 33328538, 2020). "Univariate and multivariate analyses also identified high DDX21 protein expression as an independent favorable prognostic marker for early stage MSI colorectal cancer." (PMID 33328538, 2020). "Extensive research has focused on the role of DDX21 in breast and colorectal cancers." (PMID 39769343, 2024). "RRP9 and DDX21's significant roles in colorectal cancer will be validated using public datasets." (PMID 37988222, 2023). "Additionally, the expression of DDX21 protein was examined in the verification group of 710 patients, including 619 with early colorectal cancer and 91 with advanced colorectal cancer." (PMID 37988222, 2023). "Research suggests that RRP9 and DDX21 may play a role in the development of both colorectal cancer and keloids, but their exact molecular mechanisms and regulatory pathways have not been fully elucidated." (PMID 37988222, 2023). "Furthermore, DDX21 plays its oncogenic role in colorectal cancer via inducing genome fragility, damaging double-strand repair and procrastinating HR repair." (PMID 37072811, 2023). "Another study confirmed DDX21 as a prognostic marker for early colorectal cancer with microsatellite instability, which might be a new precision treatment strategy." (PMID 36505822, 2022). "However, there are few reports about the role of DDX21 in colorectal cancer, although DDX21 has been identified as a candidate biomarker with high confidence." (PMID 35371306, 2022). "Therefore, the complex roles of this multifunctional protein DDX21 await to be explored in colorectal cancer." (PMID 35371306, 2022). "The results showed that DDX21 was dramatically upregulated in colorectal cancer cells." (PMID 34903139, 2021). "In this paper, we focus on the discovery and characterization of DEAD-box RNA helicase DDX21 in colorectal cancer since function and clinical significance of DDX21 in cancers, including survival effects, are largely unknown." (PMID 33328538, 2020). "The survival analyses thus far indicated that positive DDX21 expression may be a prognostic for better disease-free survival in early stage colorectal cancer of the MSI subtype." (PMID 33328538, 2020). "In about 20–30% of colorectal cancer cases, DDX21 overexpression was detected in cancer cells." (PMID 33328538, 2020). "We speculate that DDX21 may have an important effect on colorectal cancer and keloids." (PMID 37988222, 2023). "Specifically focusing on candidate proteins that have known antigenic properties, we selected DDX21 and investigated the protein expression of DDX21 in a large cohort of 619 patients with early stage colorectal cancer and a small cohort of 91 patients with late stage colorectal cancer." (PMID 33328538, 2020). "In addition to patient age, positive DDX21 protein expression in cancer tissue was also an independent favorable prognostic factor for disease-free survival time in the MSI subtype of early stage colorectal cancer." (PMID 33328538, 2020). "Phase-separated DDX21 facilitates epithelial–mesenchymal transition (EMT) and metastasis by binding to the MCM5 gene locus in colorectal cancer." (PMID 39866844, 2025).
colorectal cancer (continued). "And DDX21 (DExD-Box Helicase 21), a well-characterized RNA-binding protein (RBP), exhibits high expression levels in colorectal cancer (CRC), promoting CRC cell migration and invasion in vitro, as well as facilitating metastasis to the liver and lungs in vivo." (PMID 40853971, 2025). "For example, in human colorectal cancer (CRC) cells, DDX21 binds to the CDK1 promoter, interacting with WDR5 to enhance H3K4me3, which activates CDK1 expression and supports cell proliferation." (PMID 39769343, 2024). "Here, we find that DDX21, a representative RBP, is highly expressed in colorectal cancer (CRC), which leads to CRC cell migration and invasion in vitro, and CRC to liver metastasis and lung metastasis in vivo." (PMID 37029300, 2023). "The study aimed to explore the roles and interaction of DEAD-box helicase 21 (DDX21) and cell division cycle 5-like (CDC5L) in colorectal cancer (CRC) progression." (PMID 34903139, 2021). "Levels of DDX21 and CDC5L were detected in colorectal cancer cell lines by RT-qPCR and Western blot assay." (PMID 34903139, 2021). "High levels of DDX21 protein were found in 28% of stage I, 21% of stage II, 30% of stage III, and 32% of stage IV colorectal cancer cases." (PMID 33328538, 2020). "Another is Ddx21 [DEAD (Asp-Glu-Ala-Asp) box helicase 21], which has been demonstrated to be a coexpression marker with c-MYC in colorectal cancer and is known to be directly transcribed by c-Myc." (PMID 32161797, 2018). "Moreover, DExD-box helicase 21 (DDX21), a notable RNA-binding protein, is highly expressed in colorectal cancer." (PMID 38481812, 2024). "Taken together, this study uncovers that DDX21 interacted with WDR5 to promote colorectal cancer cell proliferation by activating CDK1 expression, suggesting that targeting DDX21 may be an alternative new strategy for CRC treatment." (PMID 35371306, 2022). "In vivo and in vitro experiments revealed that downregulation of DDX21 suppressed colorectal cancer cell proliferation, colony formation, cell cycle development, and tumor growth, while overexpression of CDC5L reversed the suppressive effects of DDX21 silencing." (PMID 34903139, 2021). "Despite the emerging knowledge regarding the roles of lncRNA ZFAS1 in cancers, the expression landscape, regulation network, and function manner with target proteins such as DDX21/POLR1 family have not been investigated in regard to colorectal cancer." (PMID 33202381, 2020). "In contrast, among patients with the (microsatellite instability) MSI subtype of early stage colorectal cancer, disease-free survival times (but not overall survival times) were significantly longer for the DDX21 positive group." (PMID 33328538, 2020). "Our study found that high DDX21 protein expression in cancer tissue predicts better survival for early stage colorectal cancer patients of the MSI subtype, but not for the MSS subtype or late stage cancers." (PMID 33328538, 2020). "We found high DDX21 protein expression in about 20–30% of colorectal cancer cases, regardless of cancer stage." (PMID 33328538, 2020).
gastric cancer (10 papers, 2020 to 2025). A primary or metastatic malignant neoplasm involving the stomach. "The results revealed that overexpression of DDX21 after knocking down TRIP13 rescued the proliferation restrain of gastric cancer cells caused by knocking down TRIP13." (PMID 39187490, 2024). "Aberrantly high expression of DDX21 was associated with poor OS or PFS of gastric cancer patients (log-rank P = 0.001 or 0.012; Cox regression P = 0.029 or 0.027)." (PMID 37072811, 2023). "Long noncoding RNAs LINC00240 interacted with DDX21 and stabilized DDX21 protein by preventing USP10-mediated DDX21 ubiquitination and subsequent degradation, leading to enhanced growth and metastasis of gastric cancer cells." (PMID 39866844, 2025). "Further research revealed that TRIP13 interacted with DDX21 and is significantly positively correlated in gastric cancer tissue samples." (PMID 39187490, 2024). "Mechanistically, this study confirms that TRIP13 directly interacts with DDX21 and stabilises its expression by restraining its ubiquitination degradation, thereby promoting gastric cancer progression." (PMID 39187490, 2024). "The stabilized DDX21 then promotes the upregulation of molecules associated with proliferation and EMT, thereby facilitating gastric cancer development." (PMID 39769343, 2024). "HDAC1-TRIP13/DDX21 axis provides a promising theoretical basis for treating gastric cancer patients." (PMID 39187490, 2024). "The MTT and flat clone formation assays were adopted to detect the effect of overexpression of DDX21 after knocking down TRIP13 on the proliferation ability of gastric cancer cells." (PMID 39187490, 2024). "The results of the immunohistochemistry assay demonstrate that DDX21 is highly expressed in gastric cancer tissue samples." (PMID 39187490, 2024). "Mechanically, the current study confirms that TRIP13 interacts with DDX21, and mediates the inhibition of ubiquitination degradation of the latter, thereby facilitating the progression of gastric cancer." (PMID 39187490, 2024). "Recent studies have confirmed that DDX21 is highly expressed in gastric cancer and is ubiquitinated through deubiquitinase USP10." (PMID 39187490, 2024). "For example, lncRNA HCP5 directly targets DDX21, and its downregulation inhibits DDX21 expression in gastric cancer cells." (PMID 39769343, 2024). "The experimental results identify a significant positive correlation between TRIP13 and DDX21 in gastric cancer tissue samples." (PMID 39187490, 2024). "The analysis of the R2 prognostic database further confirms that patients with high expression of DDX21 in gastric cancer with poor prognosis." (PMID 39187490, 2024). "An immunohistochemical assay was adopted to investigate the expression of TRIP13 and DDX21 in the same gastric cancer tissue samples." (PMID 39187490, 2024). "Investigation of Gene Expression Profiling Interactive Analysis (GEPIA) and TCGA databases revealed that DDX21 is highly expressed in gastric cancer patients with poor prognoses." (PMID 39187490, 2024). "Related studies have found that down-regulation of the long non-coding RNA (lncRNA) HCP5 can restrict the proliferation, migration, and invasion of gastric cancer cells by regulating expression level of DDX21." (PMID 37988222, 2023). "Rescue assays indicated that silencing of DDX21 with siRNAs significantly inhabited proliferation of gastric cancer cells with stably overexpressed LINC00240 (both P < 0.001)." (PMID 37072811, 2023). "Conversely, treatment of the stably LINC00240-OE gastric cancer cells with CHX led to an evidently longer half-life of DDX21 protein than in control cells." (PMID 37072811, 2023). "Treatment of the stably LINC00240-KD gastric cancer cells with the 26S protostome inhibitor MG132 increased expression of endogenous DDX21 protein compared to the controls." (PMID 37072811, 2023). "Intriguingly, silencing of LINC00240 evidently suppressed DDX21 protein expression in gastric cancer cells." (PMID 37072811, 2023).
gastric cancer (continued). "In gastric cancer, upregulated DDX21 increased cell proliferation in vitro and tumor progression in mice via the Cyclin D1 and CDK2 pathways." (PMID 35371306, 2022). "One study found that DDX21 promotes the proliferation of gastric cancer by regulating the cell cycle." (PMID 36505822, 2022). "The experimental results confirm that knocking down the expression of DDX21 could significantly restrain the subcutaneous tumourigenesis ability of gastric cancer cells in mice." (PMID 39187490, 2024). "Studies have shown that DDX21 is abnormally expressed in gastric cancer." (PMID 39187490, 2024). "Substantially, these results reveal that DDX21 plays the oncogene role in gastric cancer and TRIP13 could restrain the ubiquitination degradation of DDX21." (PMID 39187490, 2024). "Additionally, DDX21 directly enhances gastric cancer progression by increasing the mRNA and protein of cyclin D1 and CDK2." (PMID 39769343, 2024). "Finally, TRIP13 was found to restrain the ubiquitination degradation of DDX21, promoting the progression of gastric cancer." (PMID 39187490, 2024). "We found that DDX21 protein expression was reduced in TRIP13 knocked-down gastric cancer cells." (PMID 39187490, 2024). "Additionally, small interfering RNA was designed to knock down the expression of DDX21 to detect its effect on the subcutaneous tumourigenesis ability of gastric cancer cells in mice." (PMID 39187490, 2024). "Moreover, the use of de novo protein synthesis inhibitor cycloheximide (CHX) to detect the DDX21 turnover rate demonstrated that the DDX21 degradation rate was slowed down in gastric cancer cells overexpressing TRIP13." (PMID 39187490, 2024). "Furthermore, silencing of LINC00240 evidently suppressed DDX21 protein expression in gastric cancer xenografts." (PMID 37072811, 2023). "In contrast, more USP10 protein could be precipitated with DDX21 in the stably LINC00240-OE cells compared to the control gastric cancer cells." (PMID 37072811, 2023). "Importantly, RIP assays indicated that there was noticeable enrichment of LINC00240 in RNA–protein complexes precipitated with the anti-DDX21 antibody in both gastric cancer cell lines as compared with the IgG control (P < 0.001)." (PMID 37072811, 2023). "After knock-downing of USP10 expression, obviously decreased DDX21 protein levels could be detected in gastric cancer cells in comparation with the control cells." (PMID 37072811, 2023). "Indeed, significantly elevated DDX21 expression in gastric cancer tissues was also observed compared to normal tissues in both Discovery cohort and Validation cohort (P < 0.001)." (PMID 37072811, 2023). "On the contrary, over-expression of DDX21 could enhance cell proliferation of gastric cancer cells with stable silencing of LINC00240 with shRNAs (all P > 0.05)." (PMID 37072811, 2023). "Collectively, these findings suggested that LINC00240 could interact with oncoprotein DDX21 via the GUCT motif in gastric cancer cells." (PMID 37072811, 2023). "DDX21 has been reported to promote gastric-cancer (GC) proliferation and tumor growth." (PMID 35093935, 2022). "Endogenous DDX21 could also be precipitated with USP10 in both gastric cancer cell lines." (PMID 37072811, 2023). "These experimental results reveal that DDX21, as a binding protein of TRIP13, promotes the development of gastric cancer through its interaction with TRIP13." (PMID 39187490, 2024). "In summary, we revealed the importance of LINC00240 transcribed from the 6p22.1 locus in gastric cancer and uncovered a novel regulatory partnership between LINC00240 and USP10 in controlling ubiquitination of oncogenic protein DDX21." (PMID 37072811, 2023). "Together, these findings suggested that LINC00240 promotes DDX21 stabilization via intensifying interactions between DDX21 and its novel deubiquitinase USP10 in gastric cancer." (PMID 37072811, 2023).
gastric cancer (continued). "We also found that LINC00240 interacts with oncoprotein DDX21, suppresses its ubiquitination and stabilize the protein via intensifying binding of DDX21 with its novel deubiquitinase USP10, which, thus, leading to disease progression of gastric cancer." (PMID 37072811, 2023). "Moreover, DDX21 promoted cell proliferation through upregulation of cyclin D1 and CDK2 in gastric cancer." (PMID 39866844, 2025). "In gastric cancer, DDX21 has been shown to drive cancer cell proliferation, primarily through the activation of the cyclin D1 and CDK2 signaling pathways, suggesting that DDX21 could serve as a therapeutic target for gastric cancer." (PMID 39769343, 2024). "Importantly, LINC00240 could interact and stabilize oncoprotein DDX21 via eliminating its ubiquitination by its novel deubiquitinating enzyme USP10, which, thereby, promote gastric cancer progression." (PMID 37072811, 2023). "Importantly, LINC00240 could interact and stabilize oncoprotein DDX21 via eliminating its ubiquitination by its novel deubiquitinating enzyme USP10, which, thereby, promote progression of gastric cancer." (PMID 37072811, 2023).